EGFR (epidermal growth factor receptor)
Diseases named in the same sentence as EGFR in open-access papers (continued):
Sharing a sentence is not in itself a finding about the gene and the disease.
glioblastoma (continued). "Reports of lung, colorectal carcinoma, and glioblastoma have shown that MET is activated in the presence of EGFR blockade as a compensatory pathway, resulting in a mechanism of acquired resistance to EGFR inhibitors." (PMID 26319934, 2015). "Analysis of the TCGA glioblastoma multiforme dataset found that ZEB1 expression also shows a statistically significant increase (p value<0.05) in samples with high EGFR amplification in this dataset." (PMID 25058589, 2014). "For example, recurrent translocations in glioma cells fuse the EGFR coding sequence to several partners, EGFR-SEPT14 being the most common functional gene fusion in human glioblastoma." (PMID 24709958, 2014). "In our previous studies, the immunoliposomes were constructed by conjugating anti-EGFR antibody to liposomes using the antibody affinity motif of protein A (ZZ) as an adaptor for targeted DDS and the imaging of glioblastoma." (PMID 25190023, 2014). "This analysis enrichment of the Ras/RTK (EGFR, MAPK, RAF1, and MEK) in G-CIMP- glioblastomas is relative to the G-CIMP+ glioblastomas in both the CGGA and the REMBRANDT dataset." (PMID 25277177, 2014). "For EGFR pathway activation, the activity scores for the EGFR, MAPK, RAF1, and MEK signatures were higher in the G-CIMP- glioblastomas in the CGGA." (PMID 25277177, 2014). "Combined inhibition of DRD2 and Epidermal Growth Factor Receptor (EGFR) led to synergistic tumoricidal activity as well as ERK suppression in independent in vivo and in vitro glioblastoma models." (PMID 24658464, 2014). "Our results suggest combined EGFR and DRD2 inhibition as a promising strategy for glioblastoma treatment." (PMID 24658464, 2014). "It is well appreciated that Ras is an integral signaling constituent of many growth factor receptor pathways and that alterations in several growth factor receptor pathways, including EGFR and PDGFR, are a dominant characteristic of glioblastoma." (PMID 24438171, 2014). "They specifically investigated in more depth the genomic and proteomic data for epidermal growth factor receptor (EGFR) and phosphatase and tensin homolog (PTEN), two clinically important proteins in glioblastoma." (PMID 26556407, 2014). "Our smMIP technique detected amplification of PDGFRA, KIT and EGFR within tumor BI05, an IDH1-wild type glioblastoma." (PMID 25608559, 2014). "Although no consensus has been reached on how to assess the presence and extent of EGFR status dysregulation in solid tumors by FISH analysis, it seems likely that gene amplification found in NSCLC and glioblastoma is an uncommon event in EST." (PMID 23497641, 2013). "The CD133+ glioblastoma cell induced-tumor tissue expressed significantly higher levels of Oct4, Sox2, PCNA, EGFR, Ang2, MMP2 and MMP9 proteins compared with the CD133− glioblastoma cell induced-tumor tissue (P<0.05)." (PMID 23251243, 2013). "IPA connections of Grade IV Glioblastoma Markov genes reveled direct interactions between CD99 and ANXA2, and EGFR and RAB31 genes." (PMID 23737970, 2013). "miR-7 was reported to target EGFR and IRS2 by directly binding to their 3′-UTRs and thereby regulated the pAkt levels in glioblastoma." (PMID 23690991, 2013). "The device was able to distinguish between gliobastoma and normal host cell derived microvesicles allowing for the identification of EGFR, EGFRvIII and PDPN as markers of glioblastoma derived microvesicles." (PMID 26082318, 2013). "To address this question, we used two heterogeneous glioblastoma GSC lines (NCH421k and NCH644) that lack EGFR amplification." (PMID 24294177, 2013). "In glioblastoma cell lines U-1242 MG and U-87 MG, phorbol 12-myristate 13-acetate (PMA), an activator of protein kinase C (PKC), has been shown to activate EGFR, as judged by the phosphorylation of multiple tyrosine residues (including Y845)." (PMID 23702846, 2013).
glioblastoma (continued). "Our study demonstrates, for the first time, that vaults have a tumour-promoting potential by stabilizing EGFR/PI3K-mediated migration and survival pathways in human glioblastoma." (PMID 24243798, 2013). "To study the role of EGFRvIII in tumor angiogenesis, we prepared LN229 glioblastoma transfected with enhanced green fluorescent protein (EGFP), wild-type EGFR, or EGFRvIII (LN229-WT or -vIII), and examined tumor growth and microvessel density in the tumors." (PMID 23617883, 2013). "The epidermal growth factor receptor (EGFR, also known as HER-1) is an important target for cancer therapy and is particularly important specifically in glioblastoma pathophysiology." (PMID 23594434, 2013). "A comparison of tumor subtypes demonstrated that CD133+ glioblastoma cells had a lower incidence of cell apoptosis in the tumor tissue and higher protein expression levels of Oct4, Sox2, PCNA, EGFR, Ang2, MMP2 and MMP9 compared with CD133− cells." (PMID 23251243, 2013). "We and others have demonstrated that miR-7 inhibits EGFR expression and downstream Akt and ERK1/2 activity in lung, breast, prostate cancer and glioblastoma, leading to reduced cell proliferation and survival." (PMID 23115635, 2012). "To more directly address the capacity of glioblastoma cells to contribute to the vascular endothelium, we performed double labeling (Immunofluorescence/FISH) for the endothelial marker CD34 and EGFR gene locus." (PMID 22298889, 2012). "The EV profiles are also affected by hypoxic conditions, and the content of EGFR and PTEN modulate these responses in human glioblastoma cells." (PMID 26082068, 2012). "ELK1 is a convergence point for signaling pathways downstream of EGFR, including PI3K/Akt, and RNAi knockdown of ELK1 reduces the growth and survival of U138 glioblastoma cells." (PMID 23115635, 2012). "A total of 4974 CD34+ cells in 971 vessels were examined in the 86 glioblastomas, including 3852 CD34+ cells in 768 vessels from tumors showing EGFR amplification or gain of chromosome 7." (PMID 22298889, 2012). "Studies on other solid tumor types, most notably glioblastoma, indicate a role for IGF-1R upregulation in resistance to EGFR-targeted therapies." (PMID 21776391, 2011). "However, vice versa, EGFR was also shown to modify the HA induced expression of a number of genes associated with cellular invasion and proliferation i.e. plasminogen activator inhibitor-1 (PAI-1) or tissue inhibitor of metalloproteinases (TIMP-1) in glioblastoma cell lines." (PMID 21429221, 2011). "About 50% of glioblastomas, the most malignant and most common type of intrinsic brain tumor in adults, were found to overexpress HER1/EGFR." (PMID 20657384, 2010). "In a panel of primary glioblastoma lines, sensitivity to PARP1 inhibition correlated with the levels of EGFR activation and oxidative stress." (PMID 20532243, 2010). "In glioblastoma multiforme (GBM), EGFR overexpression and/or expression of its constitutively activated variant, EGFRvIII, result in the downstream activation of the PI3K/Akt pathway." (PMID 20975961, 2010). "EGFR is overexpressed in 40–50% of glioblastoma multiforme (GBM)." (PMID 17667926, 2007). "Of the two glioblastomas with EGFRvIII that had been detected by PAC, one had significantly (i.e. >5 fold) more mutant than wild-type EGFR transcripts." (PMID 18688287, 2007). "In glioblastoma cells, transcriptional regulation of the VEGF promoter by EGFR was reported to involve Ras/PI3K but to be distinct from signals induced by hypoxia." (PMID 19384426, 2007).
glioblastoma (continued). "However, since the present EGFR inhibitors have, at best, a small survival benefit in glioblastomas and as their use may select for further resistance-conferring mutations, there is utility in identifying additional compounds that can specifically inhibit cells with the EGFRvIII mutation." (PMID 17437646, 2007). "In this study, glioblastoma U87MG cells that were previously shown to over-express EGFR, were transfected with the antisense-EGFR constructs." (PMID 11953893, 2002). "This was also seen in hepatocellular carcinoma where it was shown that EGFR mainly acts via PI3K-PDK1 signaling to activate and regulate YAP whereas in glioblastoma, YAP nuclear translocation was regulated by EGFR through activation of the PTEN (phosphatase and tensin homolog)/Akt axis." (PMID 39936032, 2025). "Pharmacologic targeting of ALKBH5 enhanced the anti-tumor efficacy of EGFR inhibitor erlotinib, suggesting that ALKBH5 may function as a potential therapeutic target in combination with EGFR for glioblastoma patients." (PMID 40097417, 2025). "Studies have shown that in glioblastoma stem cells, there is no aggregation or close interaction between ecDNA carrying EGFR, MYC, and PDGFR, nor with transcriptional condensates, and the increase in transcriptional products is due to increased copy number." (PMID 41030947, 2025). "Currently, there is no EGFR-decorated nanoformulation that is specifically designed for MB; however, some studies have been performed on glioblastoma (GBM)." (PMID 40574048, 2025). "Although amplification of PDGF receptor genes is not an event as common as EGFR amplification in glioblastoma, PDGF receptors and their ligands are frequently up-regulated in glioblastoma cell lines and tissue samples." (PMID 40362634, 2025). "In EGFR-mutant NSCLC and glioblastoma, elevated TF predicts adverse outcomes." (PMID 40896442, 2025). "Interestingly, we found that the addition of kinase pathway inhibitors targeting EGFR and MAPK, to catalytic LSD1 inhibitors, synergistically reduced glioblastoma viability." (PMID 41497449, 2025). "A landmark preclinical study demonstrated that the dual inhibition of the EGFR/AKT and mevalonate pathways synergistically enhances the antitumor activity of TMZ in glioblastomas by inducing metabolic reprogramming and exposing vulnerabilities in energy metabolism." (PMID 41511341, 2025). "The main prognostic factors for glioblastoma (GBM) are age, performance status, histologic grade, and the presence of specific molecular markers, such as MGMT methylation, IDH1/2 mutations, 1p19q codeletion, and EGFR overexpression, according to a new classification." (PMID 40723205, 2025). "In this study, we aimed to determine whether FDX1 contributes to radioresistance in human glioblastoma cells under severe hypoxia and whether it regulates key factors such as ATM, DNA-PKcs, Akt, and EGFR, which are highly expressed in cancer cells." (PMID 40244269, 2025). "In IDH-wildtype adult diffuse gliomas, TERT promoter and EGFR amplifications are glioblastoma-defining events, even without necrosis or microvascular proliferation." (PMID 41567539, 2025). "EGFR is frequently overexpressed or dysregulated in non-small cell lung cancer (NSCLC), colorectal cancer (CRC), head and neck squamous cell carcinoma (HNSCC), and glioblastoma, where it promotes tumorigenesis and correlates with poor prognosis." (PMID 41465349, 2025). "In contrast, the EGFR/SRC/ERK signaling pathway can phosphorylate and stabilize the m6A reader protein YTHDF2, which is necessary to sustain the invasive, proliferative, and tumorigenic properties of glioblastomas." (PMID 40612868, 2025). "First-generation EGFR inhibitors, such as erlotinib or lapatinib, which have shown efficacy in other malignancies, have not demonstrated improved survival in glioblastoma patients." (PMID 39796751, 2025).
glioblastoma (continued). "Intriguingly, EGFR (rs1050171, COSM1451600) was present in 75% of the cohort overall, it showed complete penetrance (100%) in early-stage HCC, consistent with reports in glioblastoma and esophageal cancer." (PMID 41567639, 2025). "In this study, we demonstrated that in human glioblastoma-derived cell lines, T98G and A172, under severe hypoxia (with oxygen concentrations below 0.1%), FDX1 regulates the activation of key radioresistance factors, including ATM, DNA-PKcs, Akt, and EGFR." (PMID 40244269, 2025). "Expression of EGFR was restricted to only grade IV glioblastoma patients and no expression was found in astrocytoma patients grades I, II and III." (PMID 40227788, 2025). "The demonstrated synergistic efficacy (cell viability, cell proliferation, and neurosphere formation) seen in vitro for combined LSD1 and EGFR inhibition prompted an in vivo evaluation of NCD38 and osimertinib using an orthotopic glioblastoma xenograft mouse model." (PMID 41497449, 2025). "In light of the well‐established oncogenic role of EGFRvIII and the EGFR C‐terminal domain deletion mutant in glioblastoma (GBM), we sought to assess whether MIG6 possesses the capability to inhibit the enzymatic activity of these EGFR mutants and mitigate their oncogenic potential." (PMID 39129344, 2025). "Our study highlights the importance of EGFR alterations as potential biomarkers for predicting REP in glioblastoma, which could inform urgency of adjuvant therapy after surgical resection of glioblastoma." (PMID 41212363, 2025). "HGAPs do not harbor EGFR amplification, polysomy 7/monosomy 10, and rarely harbor TERT promoter mutations (1.1%), which define molecular alterations for glioblastoma." (PMID 39335555, 2024). "Additionally, growth factors such as EGFR, PDGFR, and other RTKs are often overexpressed, further contributing to glioblastoma pathogenesis." (PMID 38674436, 2024). "Here, we report that this patient relapsed with a glioblastoma displaying compound loss of function mutations in NF1, suggesting that the dacomitinib was acting on target, inhibiting EGFR and selecting for EGFR-negative subclones." (PMID 38548752, 2024). "Glioblastoma is a glial tumor that is IDH1 non-mutant with necrosis and/or microvascular proliferation or with chromosome 7 gain and chromosome 10 loss or EGFR amplification or TERT promoter mutation." (PMID 39135755, 2024). "For example, high expression of EGFR or abnormal activation is associated with the development and progression of various tumors, such as non-small-cell lung cancer (NSCLC), metastatic colorectal cancer (mCRC), head and neck cancer (HNSCC), glioblastoma (GBM), ovarian cancer, and so on." (PMID 38674402, 2024). "In gliomas specifically, in vitro cultures have been observed to develop mutations in EGFR not seen in vivo and to lose EGFR amplification, both of which are important biological drivers of IDH-wildtype glioblastomas." (PMID 38671709, 2024). "Additionally, a novel anti-EGFR antibody, GC1118, was evaluated in patients with recurrent glioblastoma." (PMID 38396993, 2024). "Traditional EGFR inhibitors fail to target the ECD of the receptor and do not effectively target EGFR conformations in glioblastoma." (PMID 38396993, 2024). "In addition, activation of the EGFR/MAPK/mTOR/AKT/ERK1/2 signaling pathway in various cancers, such as glioblastoma, endometrial cancer, and prostate cancer can promote cancer cell invasion, metastasis, and drug resistance." (PMID 38762741, 2024). "We found that Gbl17n cells, the only glioblastoma cells resistant to reovirus-induced oncolysis, lacked EGFR gene expression compared to the other primary glioblastoma cells studied." (PMID 39772250, 2024). "The analysis of the molecular docking results shows thatthe inhibition of the activity of the FGFR1, VEGFR2, EGFR, and HSP90proteins is probably not the reason for their observed selective cytotoxicactivity on glioblastoma and colorectal cancer." (PMID 38764643, 2024).
glioblastoma (continued). "Moreover, VIP blocks the invasion of glioblastoma cells (U-87MG) exposed to hypoxia by regulating HIF and epidermal growth factor receptor (EGFR) expression, which are involved in cell migration/invasion and angiogenesis." (PMID 39063232, 2024). "Moreover, molecular circuits connecting EGFR/EGFRVIII to Fyn and Src have been shown to increase glioblastoma invasion and tumour growth in a variety of cell lines and mouse models." (PMID 39697541, 2024). "Given this, we sought to uncover and characterise the PRM interactome of the RTKs epidermal growth factor receptor (EGFR), FGFR2 and ERBB2/HER2 in cell lines resembling oesophageal adenocarcinoma (OAC), breast adenocarcinoma (BrAC), glioblastoma (GBM) and lung squamous cell carcinoma (LSCC)." (PMID 39165974, 2024). "Also, the antitumor effects of this nanoparticle were investigated in the body of mice with glioblastoma, the findings of which indicated that U2-AuNP inhibits the proliferation and invasion of U87-EGFRvIII cell lines and EGFR-related pathway, preventing DNA damage repair in GBM cells." (PMID 38715021, 2024). "In an in vivo model, CAR T only injection did not eliminate tumor cells completely and allowed the growth of remaining EGFR negative glioblastoma tumor cells." (PMID 39835140, 2024). "Upregulation of EGFR pathway signaling is a common event in several kinds of chronic diseases, especially in cancers such as non-small-cell lung cancer (NSCLC), metastatic colorectal cancer, and glioblastoma." (PMID 38059627, 2024). "In summary, combining EGFR and HDAC inhibitors in glioblastoma may be able to overcome resistance clinically, but the selection of targeted therapies is important to minimize toxicities." (PMID 38183103, 2024). "In fact, the combination enhanced single-agent efficacy in glioblastoma cells independent of their EGFR status." (PMID 38183103, 2024). "However, in mixed glioblastoma cell cultures, used as a model for heterogeneous target antigen expression, NKAR-NK cells only lysed the EGFR- or ErbB2-expressing subpopulations in the presence of one of the NKAB molecules." (PMID 38334638, 2024). "In addition to EGFR, PDGF-R also serves as an important gene often overexpressed in newly diagnosed and recurrent glioblastoma." (PMID 38928445, 2024). "In glioblastoma, guanine nucleotide-binding by TG2 promotes glioma cell proliferation, survival, and invasion by interfering with the degradation of the EGF receptor (EGFR), resulting in increased EGFR signaling and subsequent cell survival." (PMID 39134806, 2024). "A study by Yin and co-workers showed that BiTE-secreting T cells EGFR and interleukin-13 receptor alpha 2 (IL13Rα2) exhibited superior antitumour activity with higher sensitivity and specificity compared to their CAR-T counterparts in glioblastoma model." (PMID 39450176, 2024). "Furthermore, another study also combined EGFR and HDAC inhibitors to study their effects on glioblastoma cells with various models of EGFR alterations." (PMID 38183103, 2024). "In contrast to EGFR, PDGFR signaling upregulates m6A levels in glioblastoma." (PMID 38398118, 2024). "incorporated an 806-based scFv into a CAR backbone and demonstrated that these EGFR806-CAR T cells conferred high anti-tumor potency in a glioblastoma in vivo model but no on-target/off-tumor activation in EGFR-positive human teratomas in the same animals." (PMID 38492569, 2024). "EGFR amplifications (7p) in glioblastoma were frequently generated from head-to-tail SVs that formed ecDNAs41,42, in contrast to the common BFB-type amplification of EGFR in oesophageal adenocarcinomas." (PMID 37198482, 2023).